ABCA11P (ATP binding cassette subfamily A member 11, pseudogene )
Synonyms: ABCA10P; ABCA11; EST1133530
Gene: Long non-coding RNA gene on chromosome 4 (425,435 to 474,129, reverse strand). Ensembl gene ENSG00000293360.
Diseases named in the same sentence as ABCA11P in open-access papers:
ABCA11P is named in the same sentence as 3 diseases in open-access papers, as found by Europe PMC text mining. Sharing a sentence is not in itself a finding about the gene and the disease. The quoted sentences say what the papers report.
glioblastoma multiforme (1 paper, 2023). "For instance, ABCA11P is associated with reduced OS in both oesophageal carcinoma and glioblastoma multiforme." (PMID 38117798, 2023).
meningioma (1 paper, 2020). A generally slow growing tumor attached to the dura mater. "Besides, potential roles of ABCA11P, ZNF732, and ZNF876P are novel in meningioma recurrence." (PMID 32923390, 2020).
ABCA11P also shares sentences with these, for which no sentence is quoted: cancer (1 paper).